BCL2 (BCL2 apoptosis regulator)
Diseases named in the same sentence as BCL2 in open-access papers (continued):
Sharing a sentence is not in itself a finding about the gene and the disease.
Wilms tumor (11 papers, 2001 to 2025). An embryonal neoplasm characterized by the presence of epithelial, mesenchymal, and blastema components. "In our study, HAGLROS silencing induced cell apoptosis by reducing cell apoptosis rate, inhibited Bcl-2 level and enhanced the activities of Bax and cleaved caspase 3 in nephroblastoma cell line HFWT." (PMID 35358010, 2022). "Midkine was found to protect Wilms' tumor cells from cisplatin-induced apoptosis through Bcl-2 enhanced expression." (PMID 24083030, 2013). "Generally, Bcl-2, Bax and for Bcl-X S/L were expressed in the blastemal and epithelial components of Wilms' tumour." (PMID 11720445, 2001). "The Wilms’ tumor gene WT1 locates at the rightmost (the highest) peak on chromosome 11; it is a tumor-suppressor gene that encodes a zinc finger transcription factor regulating transcription of growth factors such as PDGF-A, growth factor receptor (IGF-IR) and other genes (RAR-α, c-myc and bcl-2)." (PMID 29073141, 2017). "Similarly, a recent study suggests that WT1 may potentiate oncogenesis and tumor progression by transcriptionally upregulating BCL2 and that this mechanism may contribute to the heightened resistance to chemotherapy-induced apoptosis in diffuse anaplasia Wilms tumors." (PMID 40493404, 2025). "Out of 27 Wilms tumor cases, 100% displayed positivity with WT1, 22.22% with PAX8, and 7.40% with BCL2." (PMID 37908610, 2023). "For instance, among Wilms' tumor cases,an overwhelming 100% displayed positivity with WT1, while 22.22% and 7.40% exhibited positivity with PAX8 and BCL2, respectively, aligning with findings fromearlier studies." (PMID 37908610, 2023). "And immunohistochemistry showed that vimention and CK (AE1/AE3) were positive, and Bcl‐2, CD34, CK20, SMA, and WT1 (Wilms' tumor) were negative." (PMID 38767517, 2024).
amyotrophic lateral sclerosis (10 papers, 2013 to 2025). Amyotrophic lateral sclerosis (ALS) is a neurodegenerative disease characterized by progressive muscular paralysis reflecting degeneration of motor neurons in the primary motor cortex, corticospinal tracts, brainstem and spinal cord. "Similarly, GeneCOCOA also reported false positive associations in the amyotrophic lateral sclerosis (ALS) data set for the genes BCL2 and BAX." (PMID 40163580, 2025). "The protein levels of different BCL2 proteins are altered in motor neuron disease-amyotrophic lateral sclerosis (ALS), which is characterized by excessive ER stress and disturbed protein homeostasis." (PMID 40113751, 2025). "CASP3, CASP9, tumor necrosis factor (TNF), and Bcl-2 were shown to be major contributory genes in connection with flavonoid action, amyotrophic lateral sclerosis (ALS), the epithelial cell apoptotic process, and hypoxia." (PMID 37446564, 2023). "Further, Bcl-2 overexpression in a mouse model of amyotrophic lateral sclerosis (ALS) delayed disease onset and prolonged survival." (PMID 29890980, 2018). "Importantly, our analyses suggest that human iPSC-derived neurons are a relevant model system for studying the involvement of BCL2 and TDP-43 in amyotrophic lateral sclerosis." (PMID 33972534, 2021).
anemia (10 papers, 2008 to 2025). A reduction in the number of red blood cells, the amount of hemoglobin, and/or the volume of packed red blood cells. "Of the 15 variables retained by the Boruta algorithm, multivariable LR identified six significant independent prognostic factors: performance status, stage, LDH, BCL2 expression, anemia and SII." (PMID 41156312, 2025). "Healthy mature RBCs express BCL-2, which contributes to their longevity; thus, BCL-2 inhibition can lead to anemia." (PMID 41516229, 2025). "The prognostic significance of variables incorporated in our nomogram, including stage, LDH, ECOG performance status, BCL2 expression, anemia, and SII, has been well-documented in cancer prognosis." (PMID 41156312, 2025). "Consequently, we used six prognostic factors identified as significant through multivariable LR, namely, ECOG performance status, stage, LDH, BCL2 expression, anemia and SII to predict treatment response." (PMID 41156312, 2025). "Similarly, the STAT3 and BCL2 pathways—known for their roles in apoptosis and immune response—are modulated by compounds such as caffeic acid and melatonin, potentially explaining RG’s impact on allergy and anemia by promoting cell survival and reducing inflammation." (PMID 40699728, 2025). "However, Bcl-2 combined with Myc expression caused a mild anemia (data not shown) in a genotype dependent manner and induced robust B220+ B-cell development with over a 3-log increase in number compared to Stat5 knockout alone measured one month post-transplantation." (PMID 26338970, 2015). "For example, a patient with performance status (≥2), anemia, elevated LDH, high SII, positive BCL2 expression, and stage III/IV could obtain 57 points, 37 points, 52 points, 70 points, 36 points, and 100 points, respectively, resulting in a total score of 352 points." (PMID 41156312, 2025). "Additionally, our nomogram included BCL2 expression, anemia, and SII, which were not originally part of the IPI-based scoring systems." (PMID 41156312, 2025).
liver disease (10 papers, 2012 to 2025). "PI3K/Akt activation can heighten the levels of the downstream antiapoptotic protein Bcl2, promoting the activation of caspase 3, decreasing the expression of the proapoptotic protein caspase 3, preventing cell apoptosis, and improving liver disease." (PMID 40557038, 2025). "Research has demonstrated that PI3K/Akt pathway activation can elevate Bcl-2 protein levels, decrease Bax and caspase 3 proteins expression, confer protection against apoptosis, and ameliorate liver diseases." (PMID 38750545, 2024). "In this study, we established an improved high fat diet during the weaning period of NAFLD rat model to observe the expression of Bcl-2, Bax, Caspase-3 in liver tissue, in order to further clarify their roles and relationship in liver disease pathogenesis." (PMID 29324774, 2018). "Upregulation of Bcl-2 expression reduces hepatocyte apoptosis in liver diseases." (PMID 36518880, 2022). "In this study we evaluated the expression of Beclin 1 (one of the main autophagocytic agents, which bridges autophagy, apoptosis and both differentiation), and both pro- (Bad, Bax) and anti-apoptotic (Bcl-2, Bcl-xL) factors in liver samples from patients with different stages of liver disease." (PMID 22928777, 2012). "Furthermore, the cell factors (Bax, Bcl-2, COX-2 and VEGF) mediated by miR-506-3p and miR-124-3p may also involve in the pro-apoptosis role and development of portal hypertension." (PMID 34112885, 2021).
metabolic syndrome (10 papers, 2017 to 2025). A cluster of metabolic risk factors for CARDIOVASCULAR DISEASES and TYPE 2 DIABETES MELLITUS. "Moreover, in patients with metabolic syndrome, serum bcl-2 levels, which are associated with NAFLD activity, have been reported to be closely related to HOMA, BMI, and serum uric acid levels." (PMID 38169712, 2023). "Bcl2 was low expressed in metabolic syndrome, and its expression level was upregulated after exercise (P < 0.05)." (PMID 37053002, 2023). "The other clinical factors also connect with dyslipidemia, including B symptoms, BCL2 fusion translation, ferritin, and BMI." (PMID 37384286, 2023). "In terms of dyslipidemia, B symptoms, molecular typing, BCL2 fusion translation, ferritin, CRP, and IL-6 have influenced dyslipidemia (p <0.05)." (PMID 37384286, 2023). "Moreover, the BCL-2 gene showed lower expression in the MetS + 100 mg group compared to the H + 100 mg group, indicating that the balance between pro- and antiapoptotic factors of the BCL-2 family may be disrupted by the metabolic syndrome promoting the proapoptotic pathway." (PMID 39596317, 2024).
ovarian tumor (10 papers, 1995 to 2024). "The expression of bcl-2 was studied in normal ovaries and in ovarian tumours by immunohistochemical analysis." (PMID 7577491, 1995). "Our results indicate an inhibitory role of bcl-2 in development and progression of ovarian tumours." (PMID 7577491, 1995). "Supporting a clinically meaningful role for LARP1 in the post-transcriptional regulation of BCL2 and possibly also BIK expression in ovarian malignancies, expression of LARP1 positively correlates with BCL2, but is negatively correlated with BIK expression in a study of over 400 ovarian tumours." (PMID 26717985, 2016). "The immunohistochemical staining with bcl-2 and telomerase may not provide meaningful contribution for the typing of ovarian tumors." (PMID 22995373, 2012).
retinal degeneration (10 papers, 2007 to 2025). Degeneration of the retina. "Future studies will be needed to address the impact of the Bcl-2-related pathway in other inherited mutations leading to constitutive phototransduction-dependent retinal degeneration." (PMID 19672311, 2009). "Our previous work, showing that activation of the Bcl-2-related signaling pathway was associated with retinal degeneration in Rpe65-deficient mice, led us to investigate whether this apoptotic pathway was triggered by light-independent, constitutive activity of the phototransduction cascade." (PMID 19672311, 2009). "Increased ectopic expression of Bcl-2 against retinal damage protects photoreceptor cells from oxidative toxicity in transgenic retinal degeneration slow mice." (PMID 38004409, 2023). "The relative mRNA expression of the apoptosis-related genes BAX, BCL2, CASP3, CASP8, and CASP9 was analyzed to study the events associated with the apoptosis process during spontaneous retinal degeneration." (PMID 35221932, 2022). "Bcl-2 is the most prominent anti-apoptotic member and is an important regulator of photoreceptor cell death in retinal degenerations." (PMID 21851605, 2011). "Moreover, high levels of bcl-2 over-expression in photoreceptors promote retinal degeneration rather than preventing it, and so gene dosage is critical." (PMID 17375200, 2007).
Splenomegaly (10 papers, 2005 to 2024). Abnormal increased size of the spleen. "Bcl-2−/− transplanted mice developed a disease characterized by diminished leukocytosis, but as in wild type mice, developed splenomegaly and bone marrow infiltration." (PMID 24177192, 2013). "Co-expression of BCL-XL or BCL-2 together with MYC resulted in splenomegaly in all animals with mean values for moribund animals at 757 mg for BCL-XL/MYC BALB/c and 899 mg for BCL-2/MYC BALB/c mice." (PMID 22393362, 2012). "However, when TRAF3/BCL2 double-tg mice became older they began developing severe lymphoid dyscrasias, characterized by massive splenomegaly, and overt disseminated lymphadenopathy." (PMID 30687320, 2018). "It is, however, possible that other BH3-only proteins may be involved in the killing of chronically activated T cells, and lymphadenopathy and splenomegaly may therefore be even more severe in Bcl2-tg Faslpr/lpr mice than in Bcl2l11−/−Faslpr/lpr mice." (PMID 18275830, 2008). "Although AS Bcl-2 ODNs induced splenomegaly and increased serum IL-12 levels in the present experiment, suggesting an immunostimulatory effect of AS Bcl-2, the antitumor effect of AS Bcl-2 ODNs seemed to result from downregulation of Bcl-2, independently of CpG-mediated immune stimulation." (PMID 16280040, 2005). "AS Bcl-2 ODNs induced splenomegaly in association with increased serum IL-12, which was attenuated by methylation of the CpG motifs of AS Bcl-2; however, methylated CpG failed to negate the increased antitumor effect of AS Bcl-2." (PMID 16280040, 2005). "Additionally, FA downregulated the levels of inflammatory and chemotactic cytokines, alleviated splenomegaly, and exhibited anti-apoptotic effects on KD by reducing TUNEL-positive cells, downregulating BAX expression, and upregulating BCL-2 expression." (PMID 39268468, 2024). "Bcl2-Tg/Tfl-/- mice showed similar lymphadenopathy, and the size of splenomegaly was not different from Bcl2-Tg (data not shown)." (PMID 37304286, 2023). "However, given that AS Bcl-2 stimulates IL-12 secretion and results in the development of splenomegaly, effects that are not observed with methylated AS Bcl-2, Th1-mediated immunostimulation may have antitumor effects in solid tumors in humans." (PMID 16280040, 2005). "In this report, we show that the combination of TRAF3 and BCL2 overexpression in B cells leads over time to severe lymphadenopathy, splenomegaly and extranodal lymphoid infiltrations in tissues and organs in the mice, which is not observed in mice with mono-transgenic TRAF3 or BCL2." (PMID 30687320, 2018).
ulcerative colitis (10 papers, 2014 to 2025). An inflammatory bowel disease involving the mucosal surface of the large intestine and rectum. "Studies have found that acupuncture can regulate the expression of Bcl-2, Bax, Fas, and FasL proteins in rats through the Bcl-2/Bax and Fas/FasL pathways, thereby inhibiting epithelial cell apoptosis in ulcerative colitis." (PMID 40698655, 2025). "Moxibustion was previously shown to inhibit epithelial cell apoptosis by modulating Bcl-2/Bax expression in a rat model of ulcerative colitis." (PMID 26550020, 2015). "The results showed that cycloastragenol treatment improved the induced morphological changes, and in ulcerative colitis rats, this compound significantly reduced expression levels of SphK, MIP-1α, BAX, NF-κB, TNF-α, and active caspase-3, associated with BCL2 and miR-143 overexpression." (PMID 41304636, 2025). "Ulcerative colitis rats were treated with 30 mg/kg cycloastragenol, and the gene and protein expression levels of SphK, MIP-1α, B-cell lymphoma 2 (BCL2), BCL2-associated X (BAX), miR-143, NF-κB, tumor necrosis factor (TNF)-α, and active caspase-3 were assessed." (PMID 41304636, 2025). "Matching with this, the anti-apoptotic effect of SA was assessed against ulcerative colitis, as it inhibited BAX and stimulated anti-apoptotic Bcl-2 expression." (PMID 40426893, 2025). "Expression of the genes BAX, BCL2, CASP3 and CASP9 was assessed at the mRNA level in the peripheral blood lymphocytes of patients with ulcerative colitis and Crohn’s disease relative to the healthy subjects." (PMID 31159239, 2019). "In this study, we evaluate the expression of the BAX, BCL2, CASP3 and CASP9 genes at the mRNA level in the peripheral blood lymphocytes of patients with ulcerative colitis and Crohn’s disease during the disease process." (PMID 31159239, 2019).
Uterine leiomyoma (10 papers, 2016 to 2025). The presence of a leiomyoma of the uterus. "Indeed, Bcl-2 may show loss of immunohistochemical expression in uLMS, whereas it is almost always expressed in uterine leiomyomas." (PMID 35344084, 2023). "With regard to uterine smooth-muscle tumors, the previous studies showed that the expression of Bcl-2 was higher in uterine leiomyomas than in the normal myometrium." (PMID 35344084, 2023). "Previously identified molecular biologic abnormalities of uterine leiomyoma include increased estrogen and progesterone receptors, bcl-2, and aromatase cytochrome P45044." (PMID 32409692, 2020). "In agreement with our results, Kim and colleagues reported that ISL induces uterine leiomyoma cell cycle arrest, the activation of caspase-3, and the down-regulation of Bcl-2, CDK2/4, and E2F protein expression levels." (PMID 31394829, 2019). "In uterine leiomyoma, ISL induces cell cycle arrest in the subG1 and G2/M phases by increasing p21Cip1/Waf and reducing Bcl-2, cdk 2/4, and E2F, thereby suppressing the proliferation of primary uterine leiomyoma cells." (PMID 33401375, 2021).